MTOR (mechanistic target of rapamycin kinase)
Diseases named in the same sentence as MTOR in open-access papers (continued):
Sharing a sentence is not in itself a finding about the gene and the disease.
tumor (continued). "Consequently, phosphorylated 4EBP1 (p4EBP1) has been generally accepted as a marker of activated mTOR signalling and high levels in tumours have been associated with a worse outcome in several malignancies, whereas nonphosphorylated 4EBP1 has been considered a tumour suppressor." (PMID 24131622, 2013). "Furthermore, AKT1 stimulated CA916798 expression through mTOR pathway in both A549 and A549/CDDP cell lines, which was also observed in the xenografted tumor in nude mice." (PMID 23667466, 2013). "Such tumours might be better treated with signal transduction suppressors that reduce SGK1 activity, such as mTOR inhibitors." (PMID 23581296, 2013). "The finding shown here, demonstrating the strong activation of mTOR in triple negative FMC, suggests that this tumor may be a suitable model to test innovative therapies against the human TNBCs." (PMID 23587222, 2013). "Moreover, we further note that in tumor cells under physiological conditions, PI3K/AKT and AMPK converge on PRAS40 to inversely modulate mTOR activation whereby tightly controlling the balance of cell growth and autophagy to govern tumor cell growth." (PMID 23565201, 2013). "FLCN contributes to VHL-induced tumor suppression by a mechanism that does not appear to involve activation of the mTOR pathway." (PMID 23922894, 2013). "Up-regulation of mTOR also occurred in tumor tissues and was independent of BCLC stage (2.15, 1.89, 2.05, 3.88 fold in total, BCLC stages A, B, and C, respectively)." (PMID 23785399, 2013). "In the present study, we found that nab-paclitaxel treatment increased phosphorylation of Akt, mTOR, p70 S6K and 4E-BP1, a mechanism that could enhance tumor cell-related resistance to nab-paclitaxel." (PMID 24042258, 2013). "In an analysis using 64-core primary tumor tissue microarrays from the Children’s Oncology Group (COG), mTOR phosphorylation levels were elevated in 60% of alveolar and 68% of embryonal cases; PKC isozymes were upregulated in up to 69% of alveolar and 72% of embryonal cases." (PMID 23638435, 2013). "The importance of the mTOR pathway in HCC was confirmed by Llovet's group in a comprehensive study with 314 HCC and 37 non-tumor tissues using a series of molecular techniques to assess mutation, DNA copy number changes, messenger RNA and gene expression, as well as protein activation." (PMID 22470194, 2012). "Besides being directly activated by tumor-suppressor LKB1, AMPK itself regulates the activation of two other tumor suppressors, TSC1 and TSC2, which are critical regulators of Rheb and mTOR." (PMID 22353783, 2012). "On the other hand, a high dose of the ATP-competitive dual mTOR and PI3K inhibitor BEZ235 blocks both the S6K1 and 4EBP1 effector pathway and robustly affects cell proliferation with the induction of cell death in certain tumor models." (PMID 23155392, 2012). "Consistently, both IR-treated tumour types showed reduced P-mTOR (Ser2448) levels without a significant change in total-mTOR levels." (PMID 22607554, 2012). "We hypothesized that the preferential induction of apoptosis with the combination in BRAF mutant cells suggests that combined mTOR and MEK inhibition may be particularly effective for this tumor genotype." (PMID 22808163, 2012). "Inhibiting paracrine mTOR activity in non-expressing cells abrogated the tumor-promoting activities of vGPCR-expressing cells in vivo." (PMID 23316192, 2012). "Among them, FBXW7 targets mTOR for degradation and cooperates with PTEN in tumor suppression." (PMID 22292069, 2012). "Overall, the data suggest that even a radiation regimen relatively ineffective at killing tumor cells and inhibiting tumor growth may still sensitize the tumor to rejection by CTL, if sufficient signaling to repair, triggering mTOR activation, is produced." (PMID 23112958, 2012).
tumor (continued). "Treatment with tumor promoter 12-O-tetradecanoylphorbol-13-acetate (TPA) decreased PDCD4 expression, which was attributable to proteasomal degradation mediated by PI3K-Akt-mTOR-p70S6K and facilitated by MEK-ERK signaling pathway." (PMID 22272332, 2012). "Further, supporting its involvement in the mechanisms of trastuzumab responsiveness, all our patients from the group B and negative mTOR tumours were alive at the last follow-up compared with only 77% for those with positive tumours." (PMID 22454081, 2012). "This delay in tumour growth was further increased when cediranib was combined with rapamycin, an mTOR inhibitor but not when combined with CT (vincristine, cyclophosphamide, cisplatin)." (PMID 23226965, 2012). "Recent studies show that some immune cells may be stimulated by mTOR, including certain populations in the CD4 and CD8 subsets of cells that are important for anti-tumor immunity." (PMID 22680924, 2012). "Similarly, JSRV Env-induced lung tumors expressed higher levels of activated mTOR in both C57BL/6 and NOD/SCID mice relative to mock-infected mice and intense staining was observed in the majority of cells within the tumor." (PMID 23251519, 2012). "Moreover, NVP-BEZ235, a dual inhibitor of both PI3K and mTOR kinases, is a potent inhibitor of PEL cell proliferation and tumor formation in xenograft mouse models." (PMID 23316192, 2012). "Further studies plan on exploring the function of GOLPH3 and the mechanism for its up-regulation in ESCC tumor, and to clarify whether GOLPH3 modulates mTOR signalling and rapamycin sensitivity in ESCC." (PMID 23056210, 2012). "Doses of everolimus that produced an antitumor effect in a syngeneic CA20948 pancreatic rat tumor xenograft model also dramatically inhibited mTOR signaling (as measured by inhibition of 4E-BP1 phosphorylation and S6K1 signaling) in tumor, skin, and peripheral blood mononuclear cells (PBMCs)." (PMID 22824201, 2012). "Result show that miR-214 and miR-199a-3p/5p was significantly down-regulated in HepG2 cells after TG and TM treatments or anoxia, further suggesting that UPR activated XBP-1 or mTOR and ERK pathway to protect tumor cell survival though suppression of the miR-199a2/214 cluster in HCC." (PMID 22359598, 2012). "Treatment with a rapamycin analogue, an inhibitor of the mTOR pathway, considerably reduced the growth of RMS xenografts, suggesting that the IRS-1/Akt/mTOR network may have a key role in tumor progression." (PMID 22778956, 2012). "Western blot analysis of the tumor lysates showed that, as observed in vitro, mTOR inhibitors increased MAPK phosphorylation in LS174T but not in SW480 xenografts." (PMID 22401294, 2012). "In spite of the well-known role of this pathway in tumor pathogenesis and progression, genetic variants in PTEN/AKT/mTOR genes had not been well studied." (PMID 22815832, 2012). "In addition, mTOR, a major down-stream target of PI3K/Akt pathway, is well-known as an essential regulator of tumor growth and cell proliferation, protein synthesis, and the modulation of signals in various signaling pathways." (PMID 22460505, 2012). "Poor OS correlated with high tumour grade (P<0.000), overexpression of p110α (P=0.041) and mTOR (77 vs 100% in negative cases; P=0.006), and tumour recurrence in the liver (P=0.009) and CNS (P=0.011) (Kaplan–Meier; log rank test)." (PMID 22454081, 2012). "mTOR kinase activity has been previously found to be up-regulated in PCa cells in response to androgens, and the mTOR pathway is important in clinical PCa, particularly in tumours lacking expression of PTEN (phosphatase and tensin homolog)." (PMID 22194994, 2011). "Finally, the mTOR inhibitor Rapamycin enhanced the effect of GSI on RhoA expression, resulting in down regulation of phospho-Akt and increased in vitro tumor cytotoxity." (PMID 22074495, 2011).
tumor (continued). "However, using FACS analysis to detect GFP+ tumor cells in the xenotransplants on day 24, a high percentage of CD133+ cells were preserved in tumors derived from LPC-H cells expressing shRNA against mTOR." (PMID 22145042, 2011). "In contrast, there was apparent upregulation of these analytes in the specimen from the IGF1R-resistant tumor that emerged during IGF1R antibody therapy, with predominant nuclear expression of both p-mTOR (Ser2448) and p-Akt (Ser473), consistent with mTORC2 pathway activation." (PMID 21494688, 2011). "In tumor tissue, ILK is observed to induce VEGF expression by Akt-mTOR dependent pathway." (PMID 21949693, 2011). "Furthermore, rapamycin treatment can coincidentally suppress mTOR signalling, HIF-1α expression and tumorigenesis in Lkb1−/+ tumours." (PMID 21283818, 2011). "Disappointingly and in contrast to our in vitro work, we found estimated eIF4E activity did not predict response to mTOR inhibition as assessed by change in tumour cell proliferation." (PMID 21320304, 2011). "VN124-1 may also be more effective in blocking tumour growth in the CRPC model, in combination with mTOR inhibition." (PMID 20842117, 2010). "Phospho-mTOR and p-p70s6K tumour expression had no influence on disease-free and overall survival in univariate analysis (P>0.05)." (PMID 20683448, 2010). "It is also possible that AR-regulated PSA is still responsive to anti-androgens, whereas tumour growth is independent of androgens and is responsive to other signalling pathways such as mTOR." (PMID 20842117, 2010). "Changes in expression of p-HER2, p-MAPK, and p-mTOR at 4 weeks (data not shown) were about the same in control and bicalutamide-treated tumours." (PMID 20842117, 2010). "Tumors and cell lines derived from primary tumors and ascites of tumor bearing mice exhibit several characteristics in common with human EOC cell lines and tumors including AKT/mTOR activation, COX1 overexpression and VEGF overexpression and secretion (and the present study)." (PMID 20958993, 2010). "From the evidence presented here, patients with homologous recombination-defective tumours could be considered for PARP inhibitors and endometrioid subtypes could be candidates for PI3K-PTEN-Akt-mTOR therapies." (PMID 24281034, 2010). "Modulation of mTOR pathway targets in PBMC and tumor samples were concordant." (PMID 20543980, 2010). "A dose- and time-dependent induction of autophagy observed in tumor cells following cisplatin treatment is evidenced by up-regulation Beclin-1 and cisplatin-triggered activation of AMPK pathway leading to a subsequent suppression of mTOR activity." (PMID 21191146, 2010). "The MEK1/2 inhibitor also partially inhibited primary tumor growth but this was not statistically significant and not as effective as the mTOR inhibitor." (PMID 20146790, 2010). "Our results indicate that prolonged treatment with low doses of mTOR inhibitors may result in more complete and durable TSC-related tumor responses, and it would be reasonable to evaluate this strategy in a clinical trial." (PMID 19368729, 2009). "In this study, 31% of tumours showed no activation of p-mTOR, despite of a high frequency of activated Akt." (PMID 19223902, 2009). "Hypoxia induces production of vascular endothelial cell growth factor (VEGF) by tumour and stromal cells which may be partly controlled by mTOR signaling and through PI3K-Akt-mTOR pathway." (PMID 19128503, 2009). "Since caveolin-1 and the AKT/mTOR signalling cascade are independently shown to be important regulators of tumour angiogenesis, we hypothesised that caveolin-1 interacts with the AKT/mTOR pathway to drive disease progression and metastasis in RCC." (PMID 18283322, 2008). "We show that PLD1 is expressed in a subset of phospho-Akt-negative tumours that maintain phospho-mTOR expression." (PMID 17726467, 2007).
tumor (continued). "Interestingly, 6 of the 10 tumours that overexpressed PLD1 are grade 3 tumours, and 5 of these tumours are among the 7 tumours that overexpress PLD1 along with phospho-mTOR." (PMID 17726467, 2007). "Five PLD1-positive tumours were negative for phospho-Akt expression, but positive for phospho-mammalian target of rapamycin (mTOR) expression." (PMID 17726467, 2007). "Seven tumours showed positive phospho-Akt and negative PLD1 expression, and five of these tumours scored positive for phospho-mTOR." (PMID 17726467, 2007). "We found that PLD1 was expressed in six ER-positive tumours; four of these tumours showed positive phospho-mTOR expression, and two were negative for phospho-Akt expression." (PMID 17726467, 2007). "In addition, we observed the local expansion of tumor cells in the paraspinal bone in MM mice and found that the phosphorylation of PI3K, AKT, and mTOR and the expression of BCL-2 were inhibited in the local tumor tissues of both CB and But groups, just as the results presented in vitro." (PMID 41481427, 2026). "Additionally, recent research indicates that BRD7 can downregulate PD‐L1 expression by inhibiting the PI3K/AKT/mTOR/STAT3 signalling pathway, thereby enhancing the cytotoxic function of CD8+ T cells and suppressing immune evasion in NPC, which in turn inhibits tumour growth." (PMID 41510594, 2026). "In addition, protein expression of PCNA, CyclinD1, Bcl-2, Integrin α2/β1, p-FAK, p-PI3K (p85), p-AKT, p-mTOR, C-myc proteins were also significantly increased in the DLD-1 xenograft tumor treated with S. moorei and were reversed by RGD peptides in S. moorei-treated DLD-1 xenograft tumor." (PMID 39990665, 2025). "Historically, the management of this tumour has been frustrating due to the lack of effective treatments; however, therapeutic options have improved over the past decade with the introduction of sirolimus, a mammalian target of rapamycin (mTOR) inhibitor." (PMID 41389323, 2025). "VEGF signaling activates downstream pathways such as PI3K/Akt/mTOR and HIF-1α, which drive endothelial cell proliferation, migration, and survival, as well as upregulation of glycolytic enzymes like hexokinase 2, further supporting tumor metabolism and immune evasion." (PMID 41465387, 2025). "Notably, in the absence of TTP, combined inhibition of EZH2 and PI3K/mTOR signaling failed to elicit anti-tumor effects in both DKO and PPKO tumor cells, particularly under castrate conditions." (PMID 40832297, 2025). "We determined that different portions of the tumor demonstrated variability in drug response, with clinically semi-active and active DSS3 scores for trametinib (a MEK 1/2 inhibitor) and everolimus (an mTOR inhibitor) in the first contrast-enhancing organoids and the tumor–brain interface." (PMID 41155119, 2025). "May promote ICC via endotoxin production or activation of pro-tumor pathways (e.g., AMPK/mTOR)." (PMID 41018102, 2025). "Research has demonstrated that activation of the mTOR pathway increases the expression of HIF-1α and c-Myc, further upregulating glucose transporter 1 (GLUT1), glycolysis-related enzymes, LDHA, MCT1, and MCT4, thereby promoting lactate production in tumor cells." (PMID 40034817, 2025). "PD‐1 is expressed on chronically stimulated T cells, and upon engagement with PD‐L1—expressed on tumor cells, endothelial cells, DCs, and other immune subsets—it recruits SHP‐2 phosphatase, leading to dephosphorylation of key TCR signaling intermediates including ZAP70, PI3K/Akt, and mTOR." (PMID 40900811, 2025). "Studies have shown that metformin (which inhibits NF-κB nuclear translocation), rapamycin (an mTOR inhibitor), and resveratrol (an activator of the nuclear factor erythroid 2-related factor 2 [Nrf2] pathway) can suppress SASP expression, exerting anti-aging and anti-tumor effects." (PMID 41181123, 2025).
tumor (continued). "KEGG pathway analysis indicated that the PI3K/AKT/mTOR signaling pathway emerged as one of the most significantly modified pathways in BON-1 and QGP-1 cells following combination treatment, potentially elucidating the mechanism by which these two agents collectively suppress tumor proliferation." (PMID 41281753, 2025). "Its anti-tumor mechanisms involve the regulation of multiple signaling pathways, such as phosphatidylinositol 3-kinase/protein kinase B/mammalian target of rapamycin (PI3K/AKT/mTOR), nuclear factor kappa B (NF-κB), Wnt (wingless/integration 1)/β-catenin, mitogen-activated protein kinases (MAPKs)." (PMID 41487492, 2025). "MTOR inhibitors typically stabilize disease rather than induce tumor regression." (PMID 40002868, 2025). "Subjects with above-median YAP or mTOR pathway activation displayed worse overall and disease-free survival, suggesting that beyond tumor initiation, YAP and mTOR pathway activation may contribute to tumor progression and influence prognostic outcomes." (PMID 39779672, 2025). "It is worth noting that in the rescue experiment, we treated CALCA-overexpressed pNETs cells with the mTOR agonist MHY1485, which could significantly reverse the proliferation inhibition induced by CALCA overexpression and promote tumor growth and angiogenesis." (PMID 41281753, 2025). "Notably, tumor-derived secretory proteins such as cathepsin K (CTSK) can activate tumor cell migration via autocrine signaling and induce macrophage M2 polarization by binding to TLR4 receptors and stimulating mTOR-dependent pathways." (PMID 41353343, 2025). "In the A549/DDP xenograft tumor model, Western blot analysis revealed that while the total protein levels of PI3K, AKT, and mTOR remained unchanged across all treatment groups, the levels of their phosphorylated forms (p-PI3K, p-AKT, p-mTOR) were notably altered." (PMID 41480385, 2025). "Previous studies have demonstrated that the inhibition of the PI3K/AKT/mTOR pathway can reduce the numbers of MDSCs and Tregs and decrease their secretion of immunosuppressive factors, such as TGF-β and IL-10, thereby improving immune activity within the tumor microenvironment." (PMID 39972480, 2025). "mTOR inhibition has shown significant clinical success in non-malignant neurological dysfunction, suggesting they may be therapeutic in combating tumor-induced neurological dysfunction." (PMID 41301687, 2025). "Studies evaluating mTOR inhibition through Everolimus (NCT01880749, NCT01419639), Everolimus in combination with Octreotide (NCT02333565), and Vistusertib (NCT03071874, NCT02831257) have demonstrated promising results in terms of tumor volume reduction and progression-free survival." (PMID 40787520, 2025). "One consideration is that mTOR inhibitors may offer dual benefits in KTRs by both suppressing immune responses and exerting anti-tumor effects, though this has not been widely implemented in standard care as antineoplastic therapy." (PMID 40647498, 2025). "Importantly, acute mTOR inhibition with AZD8055 reduced epileptiform activity and normalizes the excitatory neuron response to physiological stimulation in functional cortex, demonstrating its ability to reverse tumor-induced neurological dysfunction in vivo." (PMID 41301687, 2025). "This patient’s tumor metabolism suggests an adaptive survival program, boosting glycolytic flux via PKM and PGK1 to meet energetic and biosynthetic demands, while downregulating ribosomal machinery to conserve resources, potentially in an mTOR-influenced and immune-suppressive context." (PMID 41367869, 2025). "In addition to mTOR, AMPK inhibits ACC activity, thereby suppressing FAS by reducing the conversion of acetyl coenzyme A, which leads to decreased lipid accumulation and ultimately inhibits tumor growth." (PMID 40696413, 2025).